LINC00951 (long independently transcribed non-coding RNA 951)
Synonyms: lincRNA-uc003opf.1; FLJ41649
Gene: Long non-coding RNA gene on chromosome 6 (40,344,342 to 40,387,365, reverse strand). Ensembl gene ENSG00000226070.
Diseases named in the same sentence as LINC00951 in open-access papers:
LINC00951 is named in the same sentence as 6 diseases in open-access papers, as found by Europe PMC text mining. Sharing a sentence is not in itself a finding about the gene and the disease. The quoted sentences say what the papers report.
head and neck cancer (2 papers, 2024). A primary or metastatic malignant neoplasm affecting the head and neck. "LINC00951 rs11752942 was also revealed to be related to head and neck cancers’ incidence in adults as well as in neuroblastoma incidence in children in Asia." (PMID 38339289, 2024).
esophageal cancer (1 paper, 2024). A primary or metastatic malignant neoplasm involving the esophagus. "Hence, we explored the contribution of four long non-coding RNAs’ polymorphisms HOTAIR rs920778, LINC00951 rs11752942, POLR2E rs3787016 and HULC rs7763881 in esophageal cancer susceptibility." (PMID 38300349, 2024).
esophageal squamous cell carcinoma (1 paper, 2021). Esophageal squamous cell carcinoma (ESCC) is a type of esophageal carcinoma (EC) that can affect any part of the esophagus, but is usually located in the upper or middle third. "Finally, a correlation study of rs11752942 (A > G) SNP located in LINC00951 (lincRNA-uc003opf.1) exon, conducted in 1493 Esophageal Squamous Cell carcinoma (ESCC) patients, revealed a distinct association of the G risk-allele with the reduced expression of LINC00951." (PMID 34449663, 2021).
cancer (1 paper, 2024). A tumor composed of atypical neoplastic, often pleomorphic cells that invade other tissues. "Regarding LINC00951, we explored the LINC00951 rs11752942, A > G (G/A) polymorphism prevalence in both cancer and healthy control groups." (PMID 38300349, 2024).
tumor (1 paper, 2020). "In another case, variant rs11752942 of LINC00951 exon is linked to the susceptibility of ESCC; risk G alleles of rs11752942 may decrease the expression levels of LINC00951 via affecting the binding of miR-149-3p, thereby regulating cell proliferation and tumor growth." (PMID 32523949, 2020).
LINC00951 also shares sentences with these, for which no sentence is quoted: neuroblastoma (1 paper).